RUNX1 (RUNX family transcription factor 1)
Diseases named in the same sentence as RUNX1 in open-access papers (continued):
Sharing a sentence is not in itself a finding about the gene and the disease.
tumor (continued). "RUNX1 has been shown to facilitate AXIN1 mediated suppression of β-catenin by inhibiting estrogen-dependent signaling, specifically in ER+ disease, where low expression of AXIN1 was associated with low RUNX1 expression, unveiling a potential mechanism for RUNX1-mediated tumor suppression." (PMID 36831308, 2023). "We found that tumor-bearing mice displayed higher levels of RUNX1 in MEPs." (PMID 37919525, 2023). "Injection of Kyn (i.p.)augmented RUNX1 expression in both healthy and tumor-bearing mice." (PMID 37919525, 2023). "In addition to AhR, which was highly active in the MEPs of tumor-bearing mice, we determined RUNX1 levels." (PMID 37919525, 2023). "RUNX1 is overexpressed in various epithelial tumors, especially in the tumor initiation stages." (PMID 37760803, 2023). "RUNX1 can function as an oncogene or a tumor suppressor gene, depending on the type of cancer." (PMID 37760803, 2023). "Finally, dendritic cell infiltration was detected in 24 tumor types for RUNX1, in 24 types for RUNX2, and in 26 types for RUNX3." (PMID 36321611, 2023). "RUNXOR can regulate RUNX1 expression by recruiting the RUNX1 protein at its 3’ end, and upon binding to promoters and enhancers, it makes it participate in chromosomal translocations in malignant cells tumours." (PMID 36817434, 2023). "In addition, AhR inhibition by SR1 downregulated Cyp1a1, Cyp1b1 and Runx1 expression in MEPs in tumor-bearing mice." (PMID 37919525, 2023). "RUNX1 expression changes are also found in solid tumours, like glioblastoma, ovarian, colon, breast, and hepatocellular carcinoma, where in tumour cells and available patient samples, it predominantly acts as a tumour suppressive." (PMID 37759525, 2023). "Furthermore, the loss of RUNX1 affects the expression of EGFR and STAT3, thereby regulating the downstream pathways and ultimately regulating the function of tumor cells." (PMID 37760803, 2023). "Tumor with low RUNX1 expression might respond better to gemcitabine therapy, suggesting the potential value of RUNX1 in PDAC." (PMID 37697370, 2023). "Furthermore, mice bearing USP10-depleted LN229 and GBM2 cells had a delayed tumor formation compared with relevant control, and these alterations were reversed by RUNX1 overexpression." (PMID 36949071, 2023). "Meanwhile, the emergence of RUNX1 mutation, upregulations of genes expression (RPS27A, RPS6, UBA52, RACK1) on tumor cells, and increased frequencies of T and NK cells with TIGIT, CTLA4, and LAG3 expression were observed after midostaurin treatment, predicting the disease progression of this patient." (PMID 37638009, 2023). "Next, we determined whether circ7379-mediated downregulation of RUNX1 is required for tumor growth and metastasis." (PMID 37564198, 2023). "Runx1 KO mice indicate the importance of Runx1 for tumor formation in hair follicle stem cells." (PMID 36766749, 2023). "In turn, the RUNX1 gene (Clusters 1 and 2) could play a dual role, being both an oncogene and tumor suppressor and is considered to be an important player in AML." (PMID 37761935, 2023). "It is worth mentioning that TGFβ1 signaling pathway is significantly upregulated in vessel co-option CRCLM tumour and contributes to the expression of the proteins that mediate the development of vessel co-option, such as runt-related transcription factor-1 (RUNX1)." (PMID 36979711, 2023). "Recent research has shown that RUNX1-related pathways may involve crosstalk between fibroblasts and tumor cells, and are closely related to the formation of CAFs." (PMID 35534796, 2022). "Moreover, miR-215-3p acts as a tumor suppressor in MM, inhibiting cell proliferation and promoting apoptosis in MM cells by targeting RUNX1 and deactivating the PI3K/AKT/mTOR pathway." (PMID 36466549, 2022). "Furthermore, we report on the elevation of tumor-specific transcription factors such as RUNX1 and GABPB1, and the reduced expression of FOXO3 that is low in the advanced group." (PMID 35626705, 2022).
tumor (continued). "In addition, RUNX1 involvement in apoptotic processes has been reported on one hand to induce apoptosis and inhibit tumor progression in neuroblastoma and leukaemia, while it contrarily seems to present an antiapoptotic effect in pancreatic and ovarian cancer." (PMID 35740337, 2022). "In addition, in HNSCC, reduced RUNX1 expression suppresses the ability of cells to migrate and proliferate in vitro and reduces tumor size in vivo." (PMID 36429115, 2022). "Depending on the type of cancer, RUNX1 can act as either an oncogene or a tumor suppressor." (PMID 36430923, 2022). "RUNX1 knockdown clearly caused an increase in p21 and a decrease in BIRC5 in the A172, KALS-1 and LN229 cell lines, suggesting that these genes represent targets of RUNX1 and strongly influence tumour suppression by causing apoptosis and cell cycle arrest." (PMID 36085167, 2022). "To functionally test whether FOXN3 and RUNX1 promoted or inhibited distinct tumor states, we performed two separate experiments." (PMID 36473848, 2022). "In summary, our results suggest that one of the tumor-suppressive effects of increased expression of miR-30d is to inhibit RUNX1 and inactivate the aerobic glycolysis signaling, forming a vigorous YTHDC1-miR-30d-RUNX1-SLC2A1/HK1 axis to repress PDAC occurrence and progression." (PMID 34021267, 2021). "In summary, miR-582-5p, which was regulated by RUNX1, inhibited tumor growth and invasion by targeting COL5A1, indicating that miR-582-5p may act as a biomarker and that the RUNX1/miR-582-5p/COL5A1 axis could be a potential therapeutic target for ccRCC." (PMID 33937021, 2021). "We also discovered that driver events in the private subclones of both samples, such as alterations in CDC27 and RUNX1, might have played a significant role in tumor progression or even neuroendocrine differentiation." (PMID 34646773, 2021). "In agreement with this hypothesis, co-expression of both Runx1 and Zeb2 in circulating tumor cells has been shown to significantly correlate with cancer reoccurrence." (PMID 34111109, 2021). "Ro5-3335, a RUNX1/CBFβ inhibitor, induced tumor cell death and led to tumor volume shrinkage." (PMID 34359780, 2021). "In vivo, the miR-582-5p induced tumor shrinkage was reversed by RUNX1 overexpression." (PMID 33937021, 2021). "In addition, in vivo assay showed that overexpression of RUNX1 alone significantly promoted tumor growth compared with the control group." (PMID 34021267, 2021). "In addition, we examined protein levels of several LPS141 tumor-promoting genes (i.e., RUNX1, c-MYC, FOSL2, RUNX2, and SNAI2) after ETC-168 treatment." (PMID 33564073, 2021). "Furthermore, KIRC tumor tissues had significantly lower levels of RUNX1 promoter methylation than that in paracancerous tissues, with decreased DNA methylation of RUNX1 notably associated with poor OS in KIRC." (PMID 34294773, 2021). "The tumor-specific SE-associated genes were enriched in important pathways, such as chordate embryonic development (RUNX2, FOXA1), regulation of cell adhesion (RUNX1, SOX2 and VEGFA), and epithelial cell differentiation (SOX9, ELF3)." (PMID 34001209, 2021). "So far, we have proved that YTHDC1-induced miR-30d may function as a tumor suppressor gene by negatively regulating RUNX1 and its downstream glycolytic genes including HK1, and SLC2A1." (PMID 34021267, 2021). "Three CpGs with a p-value less than or equal to 1.03 × 10−7 (Bonferroni significance threshold) were identified from the 450K array: three CpGs (cg11498607, cg04228935, cg05000748) at the CpG island of RUNX1 showed hypermethylation in tumor tissues compared with normal tissues." (PMID 32498288, 2020). "However, compared with the mice inoculated with both miR-21 antagomir and sh-NC, the average tumor volume and weight in mice inoculated with both miR-21 antagomir and sh-RUNX1 were both increased (p < 0.05)." (PMID 33061847, 2020).
tumor (continued). "The Ki-67 proliferation index in tumor tissues with reduced RUNX1 expression was slightly higher than in tumor tissues without reduced RUNX1 expression, but the difference was also not statistically significant (28.8% vs. 22.3%, p = 0.18), irrespective of histology." (PMID 32498288, 2020). "In addition to MYC, many tumor-associated genes such as RUNX1, FOSL2, BCL3 and ID2 are driven by SEs in diverse tumor types." (PMID 33628735, 2020). "RUNX1 is also known to function as a tumor suppressor in different types of cancer." (PMID 32498288, 2020). "Furthermore, immunohistochemistry results showed that, compared with the NC, the expression levels of RUNX1 in tumor bearing mice was lower, while those of YAP was increased (p < 0.05)." (PMID 33061847, 2020). "Researchers have demonstrated differential expression of RUNX1 in several cancers, and deregulation of RUNX1 correlates with tumour progression, which could ultimately lead to its dual role." (PMID 31592165, 2019). "We showed that Runx3 compensated Runx1 to contribute to neurofibromagenesis but that dual deletion of Runx1/3 in the Nf1fl/fl;DhhCre mice overcame the gene dose compensation and exhibited more durable effects on tumor initiation and/or maintenance." (PMID 31032403, 2019). "We hypothesize that the overexpression of RUNX1 in Mes GBM, especially in cancer stem cells, may cause tumor cells to over differentiate, thereby increasing their ability to attack and spread." (PMID 31754093, 2019). "We first investigated whether depletion of RUNX1 could have an anti-tumor effect on gastric cancer cells by using the tetracycline-inducible short hairpin RNA-mediated RUNX1 knockdown system." (PMID 29686309, 2018). "RUNX1 in TGF-β signalling pathway can participate in both tumor-suppressor and tumor-promoter arms." (PMID 29201108, 2017). "Together our findings indicate an important role for Runx1 in normal breast epithelial cells and provide evidence for the emerging concept that Runx1 may function as a tumor suppressor." (PMID 28407681, 2017). "Together these findings have revealed, for the first time, that the expression of Runx1 has a critical function in preserving epithelial morphology in mammary epithelial cells and preventing EMT; thus, Runx1 can be considered as a tumor suppressor in normal epithelial cells." (PMID 28407681, 2017). "In addition, we found tumor cell-specific loss of several transcription factors critical for maintaining differentiation: EBF1, TCF3 and RUNX1." (PMID 28692033, 2017). "Moreover, RUNX1 expression in 7 GC cell lines and 77 paired GC and non-tumor tissues was measured with real-time RT-PCR and immunohistochemistry, respectively." (PMID 26716895, 2016). "Outside of the hematopoietic context, this endothelial-epithelial RUNX1 transcriptional signature might also reflect the recently uncovered role of RUNX1 in epithelial-based tumor formation and progression." (PMID 27399214, 2016). "RUNX1 was reported to be a transcription factor and a tumor suppressor, which we validated in GC, and we observed that partial functions of miR-215 could be rescued." (PMID 26716895, 2016). "Our data indicates that reduced Runx1 transcriptional activity downregulates Rspo3 oncogene expression, upregulates GJA1 tumor suppressor gene expression, significantly delays tumor cell migration and wanes cell number, in a susceptible manner to Foxp3's stalling activity." (PMID 26735887, 2016). "RUNX, ZRSR2, and SF1 have also been reported in MDS; RUNX1 plays an important role in regulating the transcription of many tumor-suppressor genes, while ZRSR2 is an essential component of the splicing machinery, and SF1 is a component of the RNA-splicing machinery." (PMID 27959900, 2016). "Moreover, DN/Runx1-transfected tumor cells showed a significant upregulation of GJA1 in this cell line demonstrating an inhibitory role of Runx1 on GJA1 promoter." (PMID 26735887, 2016).
tumor (continued). "RUNX1 activity has been comprehensively study in physiological and tumor contexts." (PMID 26735887, 2016). "Moreover, we demonstrate that E2 and G-1 modulate the expression of miR144 and Runx1 also in main components of the tumor microenvironment like CAFs." (PMID 26030000, 2015). "In addition, in tumor homogenates from G-1 treated mice we found a decrease of Runx1 protein expression respect to vehicle treated mice." (PMID 26030000, 2015). "Worthy, G-1 triggered in vivo tumor growth and decreased Runx1 expression in SkBr3 xenografts." (PMID 26030000, 2015). "Thus, the establishment of RUNX1-Evi-1 transgenic zebrafish with the uniform phenotype of the tumor cells shows better resemblance to the feature of human MDS/AML." (PMID 26674644, 2015). "Because Runx1 is a sequence specific DNA-binding transcription factor, whether it functions as oncogene or tumor suppressor is dependent on its interaction with specific co-regulatory proteins." (PMID 26697518, 2015). "In addition, the GPER-mediated responses through miR144 and Runx1 in CAFs extend the current knowledge on the critical interactions between cancer cells and important components of the surrounding stroma toward tumor development and metastasis." (PMID 26030000, 2015). "In particular, RUNX1 was overexpressed in CYLD defective tumour cells." (PMID 25565632, 2014). "Using multivariate analysis RUNX1 expression was an independent prognostic marker for cancer specific-survival in the TN subtype when assessed against established pathological prognostic factors such as tumour size, grade, tumour type and lymph node status." (PMID 24967588, 2014). "The tumor suppressor role of RUNX2 andRUNX3 mainly relates to the antagonism between RUNX2/3 and the cancer-promoting programof ER signaling, whereas the tumor suppressor role of RUNX1 largely correlates to itsability to positively regulate the tumor-suppression program of ER signaling." (PMID 25415051, 2014). "In addition to a significant increase in CD4+T-lymphocytic infiltrate (P<0.05), RUNX1 positive tumours showed a significant increase in CD138+B- lymphocytic infiltrate (P<0.05) in ER- patients." (PMID 24967588, 2014). "Our data therefore indicate that TNBCs expressing RUNX1 represent a group of tumours with the poorest prognosis and suggest that in this subtype RUNX1 may be contributing to tumour progression." (PMID 24967588, 2014). "Interestingly, other tumor VM and angiogenic genes including RUNX1, HIF (Hypoxia-inducible factor)-1A, integrin-α5 and VEGF (vascular endothelial growth factor)-A were not affected." (PMID 24886166, 2014). "Although several lines of evidence strongly suggest that RUNX1 might act as a tumor suppressor, the precise molecular mechanisms of how RUNX1 could exert its tumor-suppressive activity have been elusive." (PMID 24078903, 2013). "There are indications that RUNX1 (AML1) isoforms can regulate CD56 expression, however it is still unclear how this may be linked to tumour aggressiveness." (PMID 23520509, 2013). "Thus, Klf4 and Runx1 depletions are sufficient to reverse and blunt Smad4 function in liver and lung metastases, respectively, which demonstrates that KLF4 facilitates Smad4’s tumor-suppressive activity in the liver and RUNX1 contributes to Smad4’s tumor-promoting activity in the lungs." (PMID 40999053, 2025). "The RUNX family—RUNX1 (Runt-related transcription factor 1), RUNX2 (Runt-related transcription factor 2), and RUNX3 (Runt-related transcription factor 3)—has been implicated in both normal development and oncogenesis, with RUNX3 functioning as a tumor-suppressor gene across multiple malignancies." (PMID 41181710, 2025). "For instance, many clinical laboratories routinely use tumor gene panels, primarily for solid tumors, which almost invariably include the KRAS gene, enabling the incorporation of detection of individual gene alterations also from the ETV6::RUNX1 ALL samples to diagnostic workflow." (PMID 40634509, 2025).
tumor (continued). "In addition, in both primary cells and the cell line, RAS inhibition caused retained dephosphorylation of the translation inhibitor 4EBP1,27 thereby inactivating it, increasing the anti-tumour effect of Ch-3 and explaining the reduction in RUNX1 protein levels." (PMID 38638836, 2024). "Furthermore, these data suggest that the AR and RUNX1 might work together to promote tumor progression, and to be useful for clinical therapeutic decision-making in AR+-TNBC." (PMID 36766786, 2023). "Thus, targeting RUNX1 may be effective in inhibiting tumor growth and enhancing the efficacy of gemcitabine therapy in PDAC, even for the GEM-resistant ones." (PMID 37697370, 2023). "In addition, RUNX1 was shown to promote cell proliferation and tumor growth in esophageal cancer." (PMID 37760803, 2023). "As a transcription factor, RUNX1 may affect tumor proliferation by regulating target genes." (PMID 37760803, 2023). "Huang and colleagues show that in tumor-bearing individuals, increased circulating kynurenine results in megakaryocyte differentiation from megakaryocytic–erythroid progenitor cells by activating the aryl hydrocarbon receptor, resulting in increased expression of RUNX1." (PMID 37919525, 2023). "More importantly, they show that reducing RUNX1 transcriptional activity may be an opportunity to improve the sensitivity of CSC/CTC to chemotherapy leading to a potential reduction in metastasis or tumor recurrence in AR+-TNBC." (PMID 36766786, 2023). "In addition, we confirmed the prevalence of CNV alterations in ARGs in COAD patients, and CNVs seem associated with higher expression of ARGs in tumor tissues, such as NF1, COL4A2, C1GALT1, SPHK1, RUNX1, implying a potential regulatory role of CNVs on the expression of ARGs." (PMID 36505481, 2022). "There are, however, tumours that appear to have simply lost RUNX1 activity, so RUNX1 may be altered in a variety of ways, reflecting RUNX1’s role as a master regulator of cell fate, with ability to interact with various other transcription factors and chromatin modifiers." (PMID 35396535, 2022). "Thus, the miR-21/RUNX1/YAP axis could be another underlying mechanism for miR-21 mediating MDSCs and tumor growth." (PMID 35634311, 2022). "However, RUNX1/ETO fusion protein interacts with HIF-1α for tumor progression." (PMID 36231060, 2022). "Indeed, in vivo studies have suggested that this may represent a tumor suppressor role, with RUNX1 able to directly repress Socs4 expression leading to increased STAT3 activity, which contributes to tumor development." (PMID 35204004, 2022). "Furthermore, miR-30d knockdown promoted cell growth, migration, invasion, and tumor angiogenesis, while RUNX1 knockdown attenuated these processes; miR-30d mimics inhibited cell growth, cell migration, cell invasion, and tumor angiogenesis, whereas RUNX1 cotransfection rescued these processes." (PMID 34021267, 2021). "An unresolved question is whether RUNX1 functions to promote tumor proliferation." (PMID 34659526, 2021). "Therefore, we hypothesized that RASSF2-mediated tumor suppression against RUNX1-ETO-expressing cells may be dependent on SARAH domain-dependent stabilization by the Hippo kinases." (PMID 32029705, 2020). "No significance was detected on survival time between RunxWT;Runx3WT;Nf1fl/fl;DhhCre and Runx1fl/+;Runx3fl/+;Nf1fl/fl;DhhCre mice, suggesting that loss of each allele of Runx1 and Runx3 only might not change tumor penetration rate." (PMID 31032403, 2019). "An unresolved question is whether RUNX1 functions to promote or suppress tumour metastasis in CRC." (PMID 31370857, 2019). "Some genetic testing methods may be feasible for determining whether tumor tissues highly express RUNX1 and the corresponding downstream genes (BCL3, MGP, and MXI1), consistent with our experimentally validated results: in positive cases, targeting RUNX1 may be a suitable optional treatment." (PMID 31754093, 2019).